NSD3 (nuclear receptor binding SET domain protein 3)
Diseases named in the same sentence as NSD3 in open-access papers (continued):
Sharing a sentence is not in itself a finding about the gene and the disease.
pancreatic cancer (6 papers, 2021 to 2025). "Another study revealed that NSD3 depletion in pancreatic cancer cells downregulates EGFR/ERK signaling-associated genes, consistent with reduced H3K36me2 levels." (PMID 41301842, 2025). "We find that NSD3 expression is strongly associated with clinical prognosis in pancreatic cancer, with genetic amplification of NSD3, low levels of NSD3 promoter methylation and immune cell infiltration to tumor sites as correlated features." (PMID 37062069, 2023). "Further studies will be needed to explore the function and underlying mechanisms of this mutation (and possible other NSD3 mutations) in the progression of pancreatic cancer." (PMID 34615858, 2021). "Further studies, however, are needed to explore the relationship between NSD3 and these known mutated genes in pancreatic cancers." (PMID 34615858, 2021). "In vivo, intratumoral injection of adeno-associated virus (AAV)-packed NSD3 shRNA potently inhibited pancreatic cancer xenograft growth in nude mice." (PMID 34615858, 2021). "Conversely, ectopic expression of NSD3-T1232A mutation significantly accelerated proliferation, migration, and invasion of pancreatic cancer cells." (PMID 34615858, 2021). "Finally, aberrant expression of NSD3 has been implicated in the development of multiple cancer types, such as lung, breast, and pancreatic cancer." (PMID 38256018, 2024). "Notably, when compared with NSD1 and NSD2, we find that NSD3 is prominently expressed, and its expression is significantly linked with clinical outcome in pancreatic cancer." (PMID 37062069, 2023). "In pancreatic cancer, NSD3 is frequently amplified and increased NSD3 expression was positively correlated with increased immune cell infiltration and increased proliferation, likely due to the infiltration of cancer-promoting immune cells." (PMID 40586874, 2025). "In contrast, in pancreatic cancer, NSD3 expression correlates positively with immune cell infiltration." (PMID 41301842, 2025). "The tumor-promoting function of NSD3 has also been reported in pancreatic cancer, where NSD3 expression is elevated in tumor tissues." (PMID 41301842, 2025). "The studies validated the consistent amplification of NSD3 and showed that the depletion of NSD3 decreases the viability and the colony formation capacity of lung and pancreatic cancer cell lines harboring the 8p amplicon." (PMID 38256018, 2024). "Next, we explored the association between NSD3 expression and described features of the tumor microenvironment (TME) in PAAD, a severe type of pancreatic cancer." (PMID 37062069, 2023). "Next we carried out a CCK8 assay, colony formation assays, and Edu assays to demonstrate that knockdown of NSD3 inhibits proliferation, colony formation, and DNA incorporation by pancreatic cancer cells." (PMID 37062069, 2023). "We also investigated the putative oncogenic role for NSD3 and its potential mechanistic actions in pancreatic cancer cell homeostasis." (PMID 37062069, 2023). "Next, we sought to externally validate our findings for NSD3 in TCGA cohort data by analyzing NSD3 expression profiles and clinicopathologic features in an independent collection of pancreatic cancer samples." (PMID 37062069, 2023). "Taken together, these findings suggest NSD3 expression influences the proliferation of pancreatic cancer cells, influences global methylation patterns in the genome of cells, and mediates downstream genes relevant to ERBB and EGFR/ERK signaling." (PMID 37062069, 2023). "Conversely, ectopic expression of the mutant and constitutively active NSD3 (T1232A) accelerated pancreatic cancer cell proliferation, migration, and invasion." (PMID 34615858, 2021). "Since NSD3 shRNA inhibited pancreatic cancer cell proliferation, we therefore analyzed its effect on cell cycle progression." (PMID 34615858, 2021). "In PanCa-1 pancreatic cancer cells, NSD3 silencing (by shNSD3-S5) or KO (koNSD3) largely inhibited H3K36 dimethylation (H3K36me2)." (PMID 34615858, 2021).
pancreatic cancer (continued). "Bioinformatics studies and results from local human tissues show that NSD3 is upregulated in human pancreatic cancer tissues, which is correlated with poor overall survival." (PMID 34615858, 2021). "In the present study, the bioinformatics studies show that NSD3 is overexpressed in pancreatic cancers, correlating with poor overall survival." (PMID 34615858, 2021). "First The Cancer Genome Atlas (TCGA) PDAC cohort, annotated as PAAD-TCGA, was consulted to examine NSD3 expression in human pancreatic cancer." (PMID 34615858, 2021). "In primary and established pancreatic cancer cells, NSD3 silencing (by shRNAs) or CRISPR/Cas9-induced NSD3 knockout potently inhibited cell proliferation, migration and invasion, while provoking cell cycle arrest and apoptosis." (PMID 34615858, 2021). "As shown, in the primary and established pancreatic cancer cells, NSD3 mRNA and protein expressions are significantly higher than those in the primary pancreatic epithelial cells (“priEpi”)." (PMID 34615858, 2021). "shNSD3-S5 resulted in over 85–90% reduction of NSD3 mRNA in the primary and established pancreatic cancer cells." (PMID 34615858, 2021). "All 12 sets of NSD3 blotting data were combined and results showed that NSD3 protein upregulation in pancreatic cancer tissues was significant (P < 0.05 vs. normal pancreatic tissues)." (PMID 34615858, 2021). "Here we showed that NSD3 silencing (by targeted shRNA) or KO (using CRISPR/Cas9 method) in pancreatic cancer cells potently inhibited H3K36m2 and expression of these oncogenic genes (Prkaa2, Myc, Irgm1, Adam12, and Notch3)." (PMID 34615858, 2021). "In established PANC-1 cells and other primary human pancreatic cancer cells (PanCa-2 and PanCa-3), NSD3 silencing by shNSD3-S5 significantly increased caspase-3 activity and TUNEL-positive nuclei ratio, indicating apoptosis activation." (PMID 34615858, 2021). "Taken altogether, we find that NSD3 expression and function is crucial to pancreatic cancer, and such features for NSD3 may be relevant to multiple cell types within the TME." (PMID 37062069, 2023). "Thus, we identified distinct signatures for site‐specific methylation of NSD3 genomic loci that were correlated with clinical states of patients with pancreatic cancer." (PMID 37062069, 2023). "Our in vitro experiments suggest that NSD3 may be relevant to gene expression regulation and growth factor signaling in pancreatic cancer." (PMID 37062069, 2023). "Furthermore, we explored the potential downstream mechanism by which NSD3 gene influences cellular gene expression by identifying significant genes correlated with NSD3 gene expression and pancreatic cancer in TCGA‐PAAD cohorts." (PMID 37062069, 2023). "Moreover, in pancreatic cancer, NSD3 expression is related to infiltration of B cells, CD8+ T cells, macrophages, neutrophils, and dendritic cells." (PMID 37062069, 2023). "We found that NSD3 may promote the progression of pancreatic cancer by promoting H3K36m2 formation and regulating proliferation‐related gene expression." (PMID 37062069, 2023). "Furthermore, we explored the function and mechanism of NSD3 in pancreatic cancer by in vitro cell experiments." (PMID 37062069, 2023). "Finally, we explored the putative oncogenic roles for NSD3 using a series of experiments with pancreatic cancer cells." (PMID 37062069, 2023). "Furthermore, NSD3 is frequently amplified, exhibits low promoter methylation, and is correlated with immune cell infiltration and enhanced proliferation of pancreatic cancer." (PMID 37062069, 2023). "In addition to protein levels, NSD3 induces global H3K36 dimethylation in pancreatic cancer cells and influences the mRNA levels for genes including ADAM28, ADAM9, BIRC3, CXCL5, DUOX2, GABRP, ITGB6, and RAB11FIP1." (PMID 37062069, 2023). "In the present study, we show that long full-length NSD3 is overexpressed in pancreatic cancer." (PMID 34615858, 2021).
pancreatic cancer (continued). "At last, we tested the potential function of NSD3 on pancreatic cancer cell growth in vivo." (PMID 34615858, 2021). "In addition, our results found that NSD3 mRNA and protein levels in local pancreatic cancer tissues were significantly higher than those in matched surrounding pancreatic tissues." (PMID 34615858, 2021). "We therefore tested the potential role of NSD3-T1232A on pancreatic cancer cell behaviors." (PMID 34615858, 2021). "Moreover, CRISPR/Cas9-induced complete NSD3 KO inhibited pancreatic cancer cell growth and induced significant apoptosis activation." (PMID 34615858, 2021). "These bioinformatics studies confirmed NSD3 mRNA upregulation in human pancreatic cancer." (PMID 34615858, 2021). "Indeed, in both established and primary human pancreatic cancer cells, shRNA-induced silencing of NSD3 induced significant anti-tumor activity by inhibiting cell viability, proliferation, migration, and invasion." (PMID 34615858, 2021). "Cell cycle arrest and apoptosis were detected in NSD3-silenced pancreatic cancer cells." (PMID 34615858, 2021). "Studies have shown that NSD3-dependent genes (Prkaa2, Myc, Irgm1, Adam12, and Notch3) could exert different cancer-promoting functions in pancreatic cancer." (PMID 34615858, 2021). "Furthermore, S6K1 phosphorylation was inhibited in pancreatic cancer xenograft tumor tissues with NSD3 shRNA AAV injection." (PMID 34615858, 2021). "Therefore, aberrant NSD3 overexpression in pancreatic cancer implied a potential role of this gene in cancer carcinogenesis and progression." (PMID 34615858, 2021). "In addition, NSD3 overexpression was also detected in different human pancreatic cancer cells." (PMID 34615858, 2021). "Therefore, regulating mTOR activation could be another key mechanism responsible for NSD3-driven pancreatic cancer progression." (PMID 34615858, 2021). "Whether NSD3 silencing exerted similar functions in other pancreatic cancer cells was also tested." (PMID 34615858, 2021). "Furthermore, NSD3 may be a potential target for the design of novel pancreatic cancer therapies." (PMID 37062069, 2023). "We also characterized a series of pancreatic cancer cell lines (AsPc‐1, BxPC‐3, Capan‐1, CFPAC‐1, MIA PaCa‐2, PANC‐1) to find that NSD3 expression is elevated to different degrees across samples." (PMID 37062069, 2023). "Here we found that NSD3 catalyzes H3K36 methylation and functions a potential driver for the malignant progression of pancreatic cancer." (PMID 34615858, 2021). "Finally, we demonstrate that knockdown of NSD3 alters H3K36me2 methylation, downstream gene expression and EGFR/ERK signaling in pancreatic cancer cells." (PMID 37062069, 2023). "As described, a set of five different shRNAs, targeting non-overlapping sequences of NSD3 (“shNSD3-S1/2/3/4/5”), were individually transduced to primary human pancreatic cancer cells (“PanCa-1”)." (PMID 34615858, 2021). "When compared to the control cells with koC, NSD3 KO potently inhibited cell proliferation (EdU-positive nuclei ratio reduction) and migration (“Transwell” assays), while provoking apoptosis activation (TUNEL-positive nuclei ratio increase) in the established pancreatic cancer cells." (PMID 34615858, 2021). "In addition, significant upregulation of a number of HMTs such as KMT5B, KMT2D (MLL2), NSD3 (nuclear SET domain-containing protein 3), PRDM16, MECOM (MDS1 and EVI1 complex locus protein) and NSD1 was observed in MCF7, MDA-MB-231, and pancreatic carcinoma PANC1 cell lines." (PMID 34884658, 2021). "In pancreatic cancer, NSD3 silencing resulted in inhibition of S6K1 phosphorylation, indicating that in the absence of the NSD3 oncoprotein mTOR was not activated." (PMID 38256018, 2024).
breast tumor (4 papers, 2016 to 2025). "NSD3 directly interacted with EZH2 and RNA polymerase II to stimulate H3K36 methylation-dependent transcriptional activation of NOTCH receptor cleavage-associated genes (including Adam12, DLL4, and Notch3), thereby activating Notch signaling to promote breast tumor progression." (PMID 34615858, 2021).
colorectal cancer (4 papers, 2014 to 2023). A primary or metastatic malignant neoplasm that affects the colon or rectum. "Furthermore, the overexpression of NSD3 was observed in cancer types including colorectal cancer and it enhances the phosphorylation levels of ERK1/2 in CRC cell lines." (PMID 37751451, 2023). "Indeed, a study by Yi and colleagues also showed that NSD3 overexpression enhanced the phosphorylation level of ERK1/2 in colorectal cancer, while inhibition of ERK1/2 significantly decreased proliferation." (PMID 37062069, 2023). "We identified cancer cell lines with NSD3 amplification for further experimental validation, including the non small-cell lung cancer (NSCLC) cell lines H1581 (7 copies Nsd3) and H-1703 (6 copies Nsd3), as well as the colorectal cancer cell line SW837 (5 copies Nsd3)." (PMID 24874471, 2014).
head and neck cancer (4 papers, 2016 to 2023). A primary or metastatic malignant neoplasm affecting the head and neck. "Additionally, we find that EGFR/ERK signaling pathway was disrupted by NSD3 knockdown, a finding that is consistent with current findings, as well as a study in head and neck cancer." (PMID 37062069, 2023).
leukemia (4 papers, 2020 to 2025). A malignant (clonal) hematologic disorder, involving hematopoietic stem cells and characterized by the presence of primitive or atypical myeloid or lymphoid cells in the bone marrow and the blood. "CHD8 was previously shown to bind BRD4 via NSD3 in leukemia cells and act as a functional CHD8-NSD3-BRD4 unit in transcriptional activation." (PMID 40104050, 2025). "In human AML leukemia cells, the short form of NSD3 could be recruited by BRD4 to Myc enhancers and activate Myc expression." (PMID 32669118, 2020). "Specifically, NSD3S, a short isoform of the NSD3 histone lysine methyltransferase, lacking methyltransferase activity, has been linked with progression of leukemia and NUT-midline carcinoma." (PMID 31638140, 2020).
lung adenocarcinoma (4 papers, 2011 to 2024). A carcinoma that arises from the lung and is characterized by the presence of malignant glandular epithelial cells. "In this study, it is proved that downregulated level of NSD3 is linked to clinical features and poor survival in lung adenocarcinoma." (PMID 39119928, 2024). "At the same time, we analyzed the mutation rates of H3K36 enzymes (including NSD1, NSD2, NSD3, ASH1L, SMYD2, SETDB2, SETD3, and SETMAR) in lung adenocarcinoma, which showed that the amplification mutation frequency of H3K36 enzymes was at a low level." (PMID 39119928, 2024). "In summary, our studies explore the vital role of NSD3 non‐epigenetic regulatory effects in lung adenocarcinoma progression and metabolism, indicating that NSD3 as a promising therapeutic target for lung adenocarcinoma." (PMID 39119928, 2024). "We also confirmed that the ability of colony formation and proliferation in lung adenocarcinoma cells are upregulated after NSD3 has been knockout, which can be furtherly inhibited by Stattic." (PMID 39119928, 2024). "We found that NSD3 inhibited the proliferation, migration, invasion, and the Warburg effect in lung adenocarcinoma." (PMID 39119928, 2024). "In this study, we comprehensively and intimately clarified the function of NSD3 in lung adenocarcinoma, a type of cancer with low expression of NSD3." (PMID 39119928, 2024). "In vivo, NSD3 inhibited the proliferation, immigration, and invasion ability of lung adenocarcinoma." (PMID 39119928, 2024). "The relative amplification of the genes varied substantially across the cancer types, with SETDB1 amplified in 20% of lung adenocarcinomas, NSD3 amplified in 21% of lung squamous cancers, and BRD4 amplified in 17% of ovarian serious adenocarcinomas." (PMID 24874471, 2014). "Together, this study revealed the critical non‐epigenetic role of NSD3 in the regulation of STAT3‐dependent glycolysis, providing a piece of compelling evidence for targeting the NSD3/PPP1CB/p‐STAT3 in lung adenocarcinoma." (PMID 39119928, 2024). "Meanwhile, NSD3 suppressed glycolysis by inhibiting HK2 translation, transcription, glucose uptake, and lactate production in lung adenocarcinoma." (PMID 39119928, 2024). "NSD3 formed protein trimer with PPP1CB and p‐STAT3, thus stimulating p‐STAT3 dephosphorylation by PPP1CB to suppress the transcription of HK2, which ultimately inhibited the Warburg effect in lung adenocarcinoma." (PMID 39119928, 2024).
myelodysplastic syndrome (4 papers, 2016 to 2023). A clonal hematopoietic disorder characterized by dysplasia and ineffective hematopoiesis in one or more of the hematopoietic cell lines. "Furthermore, genetic fusions of NSD3 with NUP98 and NUTM1 genes have been described in patients with AML as well as myelodysplastic syndrome, and primary pulmonary NUT carcinoma, respectively." (PMID 37062069, 2023).
osteosarcoma (4 papers, 2021 to 2024). A usually aggressive malignant bone-forming mesenchymal neoplasm, predominantly affecting adolescents and young adults. "In a human osteosarcoma cell line, NSD3 silencing resulted in the inhibition of cell proliferation, induction of apoptosis, and an increase in the number of cells in th eG2/M phase, suggesting a role for NSD3 in G2/M cell cycle arrest." (PMID 38256018, 2024).
breast invasive carcinomas (2 papers, 2014). "Another example is the H3K36 dimethylase WHSC1L1/NSD3 amplified and overexpressed in 18% and 8% of lung squamous cell and breast invasive carcinomas, respectively." (PMID 25484917, 2014).
esophageal SCC (2 papers, 2017 to 2024). "A study of structural variations in esophageal squamous cell carcinoma (ESCC) found that chromothripsis leads to high-level amplification of FGFR1, LETM2 and NSD3 on chromosome 8." (PMID 38256018, 2024). "Several studies have reported the detection of fusion genes in SCC of other organs (AML4-ALK in lung SCC, FGFR3-TACC3 in head and neck SCC, NSD3-NUT in NUT midline carcinoma, and GOLM1-MAK10 in esophageal SCC)." (PMID 28978917, 2017).
thyroid carcinomas (2 papers, 2022 to 2023). "In this report, we present a high-grade thyroid carcinoma with an NSD3::NUTM1 fusion detected on expanded next-generation sequencing testing." (PMID 34997561, 2022). "In summary, we present an NSD3::NUTM1 fusion thyroid carcinoma clearly showing thyrocyte differentiation, including colloid production and poorly formed follicles." (PMID 34997561, 2022). "This case is the first reported of a thyroid carcinoma exhibiting thyrocyte differentiation and an NSD3::NUTM1 fusion." (PMID 34997561, 2022). "The NUT::NSD3 gene fusion has recently been described in a subset of thyroid carcinomas without classical features, so that there is a rationale for NUT immunohistochemistry and/or molecular testing in unusual cases." (PMID 37118352, 2023). "Thus, at the molecular genetic level, three of the now four reported cases of primary thyroid carcinomas with NUTM1 fusions, including our case, contained the NSD3 fusion partner." (PMID 34997561, 2022).
brain tumors (1 paper, 2022). "Set2 homologs, including NSD1, NSD2, NSD3, and SETD2, are frequently mutated, translocated, or amplified in a variety of human cancers, and oncohistone mutations that dysregulate H3K36 methylation cause pediatric brain tumors." (PMID 35263330, 2022).
cancers of the brain (1 paper, 2016). "NSD1 has been implicated in cancers of the brain such as glioma and neuroblastoma and there has been extensive work done on characterization of the NSD family including crystal structures for each of NSD1 / NSD2 and NSD3." (PMID 26781748, 2016).
colon cancers (1 paper, 2023). "Importantly, the ET domain is also associated with a variety of cellular proteins such as NSD3 and JMJD6, which are implicated in the development of AML and lung/colon cancers, respectively." (PMID 37049806, 2023).